KLC1 (kinesin light chain 1)
Description:
Kinesin is a microtubule-associated force-producing protein that may play a role in organelle transport. The light chain may function in coupling of cargo to the heavy chain or in the modulation of its ATPase activity (By similarity).
Synonyms: KLC; KNS2; KNS2A; hKLC1S; hKLC1N; hKLC1P; hKLC1G; hKLC1R; hKLC1J; hKLC1B
Tractability: Small molecule: it has a binding pocket of medium quality. Antibody: the Human Protein Atlas places it where antibodies can reach. PROTAC: ubiquitination databases record sites on it; its protein half-life has been measured.
Gene: Protein-coding gene on chromosome 14 (103,561,896 to 103,714,249, forward strand). Ensembl gene ENSG00000126214.
Subcellular location: Cell projection, growth cone; Cytoplasmic vesicle; Cytoplasm, cytoskeleton
Subcellular location (Human Protein Atlas): Acrosome; Equatorial segment; Plasma membrane; Cytosol; Nucleoplasm
Pathways (Reactome):
Disease: Signaling by ALK fusions and activated point mutants
Hemostasis: Kinesins
Immune System: MHC class II antigen presentation
Signal Transduction: RHO GTPases activate KTN1
Vesicle-mediated transport: COPI-dependent Golgi-to-ER retrograde traffic
Gene Ontology:
Molecular function: protein binding; cytoskeletal motor activity; kinesin binding
Biological process: microtubule-based movement; stress granule disassembly
Cellular component: cytoplasmic vesicle; membrane; cytoplasm; cytosol; growth cone; kinesin complex; cytoskeleton
Genetic constraint (gnomAD): Loss-of-function variants: 25 observed, 69.08 expected, observed/expected ratio (o/e) 0.36, 90% interval 0.26 to 0.5. The upper end of that interval is the gene's LOEUF score, 0.5, which puts it in group 2 of 6, group 1 being the genes least tolerant of losing a copy. Missense variants: 450 observed, 743.78 expected, observed/expected ratio (o/e) 0.61, 90% interval 0.56 to 0.65. Synonymous variants: 265 observed, 277.95 expected, observed/expected ratio (o/e) 0.95, 90% interval 0.86 to 1.06.
Homologues: Orthologues: chimpanzee KLC1 (99% identical), dog KLC1 (96% identical), pig KLC1 (95% identical), mouse Klc1 (94% identical), rat Klc1 (93% identical), guinea pig KLC1 (93% identical), rabbit KLC1 (92% identical), macaque KLC1 (87% identical), tropical clawed frog klc1 (82% identical), zebrafish klc1a (81% identical), Drosophila melanogaster Klc (57% identical), Caenorhabditis elegans klc-2 (52% identical), and 1 more. Paralogues in human: KLC2 (66% identical), KLC4 (66% identical), KLC3 (48% identical), NPHP3 (30% identical), APPBP2 (18% identical).
Diseases named in the same sentence as KLC1 in open-access papers:
KLC1 is named in the same sentence as 53 diseases in open-access papers, as found by Europe PMC text mining. Sharing a sentence is not in itself a finding about the gene and the disease. The quoted sentences say what the papers report.
Alzheimer disease (7 papers, 2007 to 2024). A progressive, neurodegenerative disease characterized by loss of function and death of nerve cells in several areas of the brain leading to loss of cognitive function such as memory and language. "Recent studies showed that KLC1 Serine460 phosphorylation causes axonal transport deficits and contributes to neurodegeneration in Alzheimer’s disease." (PMID 38363426, 2024). "Genetic variability for KLC1 is thought to be a risk factor for early-onset of Alzheimer's disease." (PMID 24086147, 2013). "Recently, a polymorphism in the KLC1 gene (rs8702, 56,836G>C), localized in a non-coding region that may regulate alternative splicing of the KLC1 gene transcript, was associated with Alzheimer disease (AD)." (PMID 17653041, 2007). "Thus, LMTK2 binds to KLC1 to direct axonal transport of p35 and its loss may contribute to Alzheimer’s disease." (PMID 31068217, 2019). "For example, in rats afflicted with parkinsonism and in patients afflicted with ALS and Alzheimer's disease, the content of kinesin reduces; however, the KLC1 level in patients with breast cancer was witnessed to be remarkably increasing." (PMID 32215272, 2020). "Our results suggest that increased KLC1 serine-460 phosphorylation contributes to Alzheimer’s disease." (PMID 31806024, 2019). "Here we demonstrate that in Alzheimer’s disease frontal cortex, KLC1 levels are reduced and the relative levels of KLC1 serine-460 phosphorylation are increased; these changes occur relatively early in the disease process." (PMID 31806024, 2019). "Together, these results suggest that increased KLC1 serine-460 phosphorylation contributes to Alzheimer’s disease." (PMID 31806024, 2019). "Our findings are therefore the first to identify changes in phosphorylation of a defined site in kinesin-1 motor complexes in Alzheimer’s disease brain (KLC1 serine-460)." (PMID 31806024, 2019). "To do so, we monitored both total and serine-460 phosphorylated KLC1 levels in post-mortem control and Alzheimer’s disease frontal cortex tissues by immunoblotting." (PMID 31806024, 2019). "Here, we test the hypothesis that the rs8702 polymorphism in the kinesin light chain 1 gene (KLC1), previously linked to Alzheimer disease (AD), may play a role in cataractogenesis." (PMID 17653041, 2007). "We next utilised this antibody to enquire whether KLC1 serine-460 phosphorylation might be altered in Alzheimer’s disease." (PMID 31806024, 2019). "Finally, we show that KLC1 levels are reduced and the relative levels of KLC1 serine-460 phosphorylation are increased in Alzheimer’s disease frontal cortex, and that this occurs relatively early in the disease process." (PMID 31806024, 2019). "Finally, we show that KLC1 levels are reduced and the relative levels of KLC1 serine-460 phosphorylation are increased in Alzheimer’s disease frontal cortex." (PMID 31806024, 2019). "Reduced levels of both KLC1 and KLC2 have been described in late stage Alzheimer’s disease cortex (Braak stage V/VI)." (PMID 31806024, 2019). "Here, we address the role of KLC1 serine-460 phosphorylation in APP axonal transport and processing, and in Alzheimer’s disease." (PMID 31806024, 2019). "Reduction of KLC1 levels has been shown to impair APP axonal transport in rodent and Drosophila neurons and to exacerbate Alzheimer’s disease phenotypes." (PMID 31806024, 2019). "There is also evidence that phosphorylation of KLC1 is increased in Alzheimer’s disease cortex although such studies have not identified altered phosphorylation of any specific residues." (PMID 31806024, 2019). "Since we also present evidence that KLC1 serine-460 phosphorylation affects axonal transport and processing of APP, our results suggest that increased KLC1 serine-460 phosphorylation contributes to the pathogenesis of Alzheimer’s disease." (PMID 31806024, 2019).
breast carcinoma (6 papers, 2020 to 2025). "Since a recent study demonstrated the essential role of the upregulation of KLC1 expression in the oncogenesis of breast cancers, this point should be addressed in future studies." (PMID 38201436, 2023). "KLC1’s role in breast cancer, as a suppressor of epithelial-mesenchymal plasticity and translocation to the 5′ end of anaplastic lymphoma kinase (ALK), has been described previously." (PMID 36010968, 2022). "GLS, YY1AP1, FBXO22, KLC1, CUL4A, KITLG, and CYRIB are changed by AS that may be linked to the emergence of breast cancer." (PMID 40384436, 2025). "Similarly, the kinesine-1 subunits kinesin family member 5B (KIF5B)/kinesin light chain 1 (KLC1) modulate the EMP process differently in breast cancer, with KIF5B being an inducer of EMT and KLC1 being its suppressor." (PMID 36890838, 2023). "KLC1 has also been found to interact with KIF5B, regulating cell-cell adhesion, and epithelial-mesenchymal plasticity in breast cancer." (PMID 38923999, 2024).
schizophrenia (6 papers, 2014 to 2025). A major psychotic disorder characterized by abnormalities in the perception or expression of reality. "At the same time, we determined the methylation profile associated with the schizophrenia risk haplotype within the KLC1 fourth intron and confirmed ASM for cytosines located in the vicinity of rs67899457." (PMID 32170143, 2020). "At the same time, we have shown that the schizophrenia risk haplotype within the fourth intron of KLC1 associates with specific methylation profile irrespective of the diagnosis and confirmed ASM for cytosines located in the vicinity of rs67899457." (PMID 32170143, 2020). "Moreover, STAG1 and KLC1 have fine-mapped common variant signals in schizophrenia." (PMID 40753099, 2025). "Previous studies of schizophrenia cases revealed differential methylation of several cytosines located within this locus, primarily in the KLC1 body." (PMID 32170143, 2020). "We also observed association between schizophrenia and reduced fetal brain expression of a transcript of KLC1, encoding Kinesin Light Chain 1 (P-SMR = 2.95 × 10− 7), which has recently been implicated in schizophrenia risk through a splicing QTL in the adult brain." (PMID 30419947, 2018). "Variation at KLC1 provided strong evidence of colocalization in our study (combined PPA = 97.9%), where the highest individual posterior probability suggested that both gene expression and DNA methylation may be involved along the causal pathway to schizophrenia risk." (PMID 30820025, 2019).
lung carcinoma (5 papers, 2012 to 2025). "For instance, it has been demonstrated that drug resistance and lung cancer metastasis are significantly influenced by the interaction between KLC1 and ALK." (PMID 40421300, 2025). "Among these, KLC1-ALK represents a novel oncogenic fusion identified in lung cancer, while the KLC1-ROS1 fusion exerts oncogenic properties in glioma cells via specific activation of the JAK-STAT pathway." (PMID 40228435, 2025). "Wang and his/her colleagues reported a case of lung cancer with both MET gene amplification and KLC1-ALK fusion, this patient had a good response to Crizotinib." (PMID 37658352, 2023). "In the present study, we developed a 5′-RACE method optimized for ALK fusion partner detection that was applicable to FFPE tissues and identified a novel fusion, kinesin light chain 1 (KLC1)-ALK, in lung cancer by using only an FFPE tissue." (PMID 22347464, 2012). "Of the 3 histopathologically confirmed ALK fusion partners in lung cancer, EML4 colocalizes with microtubules and may contribute to the stabilization of microtubules, KIF5B moves on the microtubules as a kinesin heavy chain, and KLC1 binds to kinesin heavy chains as a kinesin light chain." (PMID 22347464, 2012). "Other less common rearrangements detected in lung cancer patients include KIF5B-ALK (kinesin family member 5B-ALK), TFG (trafficking from ER to golgi regulator)-ALK, KLC1 (kinesin light chain-1)-ALK, PTPN3 (protein tyrosine phosphatase non-receptor type 3)-ALK, STRN (striatin)-ALK." (PMID 39457620, 2024).
glioma (4 papers, 2022 to 2025). A benign or malignant brain and spinal cord tumor that arises from glial cells (astrocytes, oligodendrocytes, ependymal cells). "In glioma, the fusion of KLC1 with ROS1 activates the JAK-STAT pathway." (PMID 38923999, 2024). "Of note, KLC1 is a favorable prognostic marker in pancreatic cancer (p < 0.001) and an unfavorable prognostic marker in renal cancer with highest median expression in gliomas (TCGA dataset)." (PMID 36010968, 2022). "KLC1 and TOP2A showed high levels of expression in almost every tumor type examined, while UCHL1 was found mainly in glioma." (PMID 36010968, 2022). "Here, we investigated the detailed molecular oncogenic mechanisms of a novel receptor tyrosine kinase (RTK) fusion, KLC1-ROS1, with an adapter molecule, KLC1, and an RTK, ROS1, discovered in pediatric glioma, and we explored a novel therapeutic target for glioma that possesses oncogenic RTK fusion." (PMID 38201436, 2023).
virus infection (4 papers, 2015 to 2025). "Increased levels of KLC1 were observed starting at 6 hpi, suggesting that virus infection stimulates KLC1 synthesis." (PMID 40668623, 2025). "Noteworthy, KLC1 has been studied in the context of other viral infections and was proposed to be involved in the anterograde transport of viral cargoes, positioning it as a frequent target of viral effectors." (PMID 40668623, 2025). "As before, F12-HA co-precipitated with KLC2 during virus infection, but only background levels were detected with KLC1." (PMID 25760349, 2015). "However, virus infection of cells expressing a KLC1/2 chimaera (Flag‐KLC1/2 A) that bound both A36 and F12/E2, so that all components may be present in the same complex, showed reduced A36‐KLC interaction in the absence of F12 or E2." (PMID 28485852, 2017). "HEK TRex-F12-HAco cells transfected with plasmids expressing Flag-KLC1 or 2 were co-transfected with the V5-E2co expressing plasmid or empty vector control in the absence of virus infection." (PMID 25760349, 2015). "Interestingly F12, unlike A36, discriminated between different KLC isoforms, associating with KLC2 but not KLC1 and the F12/KLC2 association was only detectable in the presence of virus infection." (PMID 25760349, 2015).
cataract (3 papers, 2007 to 2022). Partial or complete opacity of the crystalline lens of one or both eyes that decreases visual acuity and eventually results in blindness. "KLC1 was reported to be a novel susceptibility gene for age-related cataract, and the GG genotype of rs8702 was also significantly associated with cataract patients." (PMID 23776437, 2013). "Indeed, there was a difference in KLC1 rs8702 allele and genotype frequencies between cataract patients and control individuals, which seemed to be a general finding not dependent on cataract type." (PMID 17653041, 2007).
bladder cancer (2 papers, 2022 to 2025). "Our proteome-wide MR suggested a possible association between higher KLC1 levels and increased risk of bladder cancer." (PMID 39898788, 2025). "For all 3 proteins (GSTM1, GSTM4, and KLC1), there was strong evidence of colocalization (ie, PH4 ≥ 0.8), indicating that the protein and bladder cancer share a joint causal variant." (PMID 39898788, 2025). "Higher plasma kinesin light chain 1 (KLC1) was associated with a statistically nonsignificant increased risk of bladder cancer after FDR correction." (PMID 39898788, 2025). "The associations of GSTM4 and KLC1 but not GSTM1 with bladder cancer risk were replicated (FDR < 0.1) using the corresponding cis-pQTLs from the Fenland study." (PMID 39898788, 2025). "Previous studies revealed that kinesin family members [Kinesin family member C1 (KIFC1), Kinesin family member 5B (KIF5B), and Kinesin light chain 1 (KLC1)] play important roles in accelerating epithelial−mesenchymal plasticity in bladder cancer and breast tumors." (PMID 35811688, 2022).
COVID-19 (2 papers, 2022 to 2024). A disease caused by infection with severe acute respiratory syndrome coronavirus 2. "For example, the protein KLC1 was significantly associated with hospitalized and severe COVID-19 in the cis-analysis, with rs12884809 being the IV." (PMID 40303168, 2024). "We reported that an increased plasma KLC1 level was associated with an increased risk of severe and hospitalized COVID-19." (PMID 40303168, 2024). "In conclusion, our study identified proteins with evidence of causal association with different stages of COVID-19, including novel proteins such as KLC1, MRVI1, CACO2, and PCNP." (PMID 40303168, 2024). "We found that Vitamin D carries two interesting hits suggesting causal pathways from Vitamin D concentration to the severity of COVID-19, namely, the genes KLC1 and ZFYVE21." (PMID 36156592, 2022). "Kinesin-1 is comprised, in part, of KLC1, a molecular motor protein known to play a role in the spread of many viruses and may have a role to play COVID-19's hijacking of the cytoskeleton." (PMID 40303168, 2024). "Both STAT3 and KLC1 were retained after colocalization analysis, however only STAT3 colocalized with severe COVID-19." (PMID 40303168, 2024).
dementia (2 papers, 2019 to 2021). Loss of intellectual abilities interfering with an individual's social and occupational functions. "We studied total KLC1 and serine-460 phosphorylated KLC1 levels in frontal cortex in control, Braak stage III-IV (mid dementia) and Braak stage VI (severe dementia) cases." (PMID 31806024, 2019).
depression (2 papers, 2021 to 2023). "The results indicated that Atp6v1f, Arpc5, Adcyap1r1, Ndufb6, and Psmc6 were distinctly dysregulated in the hypothalamus of the depression-susceptible group, while Gys1, Pgp, Klc1, Chka, Ncstn, Ndufa6, and Kyat1 were distinctly dysregulated in the anxiety-susceptible group." (PMID 33737865, 2021).
adenocarcinoma in situ (1 paper, 2012). A lesion in which the normally situated glands are partially or completely replaced by atypical cells with malignant characteristics. "Another important point is that KLC1-ALK was found in adenocarcinoma in situ, nonmucinous (formerly called bronchioloalveolar carcinoma, BAC)." (PMID 22347464, 2012).
amyloid (1 paper, 2012). "The reduced extracellular Aβ from KLC1-reduced hESC derived human neural cultures agrees with reports of reduced amyloid plaque loads following mechanical disruptions in axonal transport in the perforant pathway of APP transgenic mice." (PMID 22272245, 2012).
Anxiety (1 paper, 2021). Intense feelings of nervousness, tension, or panic often arise in response to interpersonal stresses. "It was observed that the expressions of Gys1, Chka, Ncstn, and Ndufa6 were significantly down-regulated whereas Pgp, Klc1, and Kyat1 were up-regulated in the anxiety-susceptible group as compared to the control group." (PMID 33737865, 2021).
Ataxia (1 paper, 2025). Ataxia refers to impaired coordination of voluntary muscle movement. "One variant each was identified in the genes CHD6 (p.Glu2697Thrfs*29 in a patient with adolescence‐onset generalized dystonia with myoclonus and ataxia), KLC1 (c.*1+1G>A in a patient with adult‐onset cervical dystonia), and NR4A2 (p.Gln273Arg in a patient with adult‐onset cervical dystonia)." (PMID 40533913, 2025).
cervical dystonia (1 paper, 2025). "This included a novel frameshift variant in CHD6 in a patient with adolescence‐onset generalized dystonia and myoclonus, as well as a novel splice‐site variant in KLC1 in a patient with late‐onset cervical dystonia without additional features." (PMID 40533913, 2025).
colon cancer (1 paper, 2022). "Furthermore, we observed mutations affecting FGFR4, KLC1 and XRCC3, associated to colon cancer and melanoma." (PMID 35836575, 2022).
colorectal carcinoma (1 paper, 2023). A malignant epithelial neoplasm that arises from the colon or rectum and invades through the muscularis mucosa into the submucosa. "To further verify whether this knockout pipeline is applicable for other genes and cell lines, we introduced a 27-kb deletion into the genomic locus of kinesin light chain 1 (KLC1) gene in a near-diploid human colorectal carcinoma cell line HCT116 in addition to RPE1 cells." (PMID 36762651, 2023).
developmental delay (1 paper, 2025). "In 2020, CHD6, KLC1, and ZMYND11 were linked to early‐onset dystonia combined with developmental delay or intellectual disability." (PMID 40533913, 2025).